CYP24A1 (cytochrome P450 family 24 subfamily A member 1)
Diseases named in the same sentence as CYP24A1 in open-access papers (continued):
Sharing a sentence is not in itself a finding about the gene and the disease.
nephrolithiasis (30 papers, 2015 to 2025). The presence of a calculus in the pelvis of the kidney; this is most often composed of mineral salts and proteins. "The frequency of kidney stones due to CYP24A1 deficiency was estimated between 420 and 1960 per 10,000." (PMID 38504242, 2024). "As such, our measurements of the VMDR in both idiopathic calcium-kidney stone formers and unselected kidney stone formers therefore offer a comprehensive view of biochemical and clinical traits associated with CYP24A1 activity." (PMID 38765596, 2024). "A recent meta-analysis identified 20 nephrolithiasis-associated loci, including CYP24A1, DGKD, DGKH, WDR72, GPIC1, and BCR locus which were predicted to affect vitamin D metabolism and calcium-sensing receptor signaling respectively." (PMID 35439979, 2022). "The clinical spectrum of the conditions induced by homozygous mutations of the CYP24A1 gene spans from idiopathic infantile hypercalcemia in children to recurrent nephrolithiasis and/or nephrocalcinosis with hypercalciuria in adulthood." (PMID 34959915, 2021). "In a validation cohort of only nephrolithiasis patients, the CYP24A1-associated locus correlates with serum calcium concentration and a number of nephrolithiasis episodes while the DGKD-associated locus correlates with urinary calcium excretion." (PMID 31729369, 2019). "In a validation cohort of nephrolithiasis patients, we find that the CYP24A1-associated locus correlates with serum calcium concentration and number of kidney stone episodes and that the DGKD-associated locus correlates with urinary calcium excretion." (PMID 31729369, 2019). "Variants in CYP24A1 are rare but they have a distinct and recognisable biochemical phenotype, and patients may present at any age with nephrocalcinosis and kidney stone formation." (PMID 40917505, 2025). "Given the high phenotypic similarity between carriers of pathogenic CYP24A1 variants and kidney stone formers with idiopathic hypercalciuria, we hypothesized that reduced CYP24A1 activity may be an important cause of idiopathic hypercalciuria." (PMID 38765596, 2024). "More recently, monoallelic mutations and polymorphisms affecting CYP24A1 activity have been implicated in a subset of patients diagnosed with idiopathic hypercalciuria who are predisposed to nephrolithiasis and nephrocalcinosis, but the clinical picture is less severe than with IHH." (PMID 39337491, 2024). "Our study conducted in 2 large and deeply phenotyped Swiss cohorts of kidney stone formers now reveals that the VMDR (and hence the activity of CYP24A1 inversely) is directly associated with urinary calcium, the key prolithogenic abnormality in kidney stone formers." (PMID 38765596, 2024). "In addition, the father of patient 5 carrying CYP24A1 mutation had kidney calculus, as well as his mother and sister." (PMID 38504242, 2024). "Based on gene frequency studies, Nesterova and colleagues estimate that the frequency of kidney stones in the general population due to CYP24A1 mutations might be as high as 4–20%." (PMID 35956396, 2022). "Long-term screening with reference to kidney function and nephrolithiasis seems to be reasonable in patients with pathogenic CYP24A1 mutations, but whether any chronic drug treatment should be advised requires further investigations." (PMID 35745247, 2022). "Additional prospective, diet-controlled clinical trials including 24,25-hydroxyvitamin D/25-hydroxyvitamin D ratio determination or genotyping for CYP24A1 should be performed to better investigate the role of mineral and bone derangements on the risk for kidney stones." (PMID 34959915, 2021). "Several alleles associated with other traits of interest: rs2836882 near PSMG1 associated with ulcerative colitis, multiple SNPs including rs3923 near SLC17A1 associated with disorders in mineral metabolism, and rs17216707 near CYP24A1 associated with nephrolithiasis." (PMID 33547301, 2021).
nephrolithiasis (continued). "Thus, we identify a locus ~38 kb upstream of CYP24A1 (rs17216707) and demonstrate that genotype at this locus is associated with serum calcium concentration and stone recurrence episodes in a cohort of kidney stone patients." (PMID 31729369, 2019). "However, our findings suggest that supplementation may put individuals homozygous for the CYP24A1 increased-risk allele at risk of kidney stones; studies are required to investigate this hypothesis further." (PMID 31729369, 2019). "Monoallelic variants of other genes, such as CYP24A1 and SLC34A1, have also been proven to have a role in increasing the risk of kidney stones." (PMID 40428323, 2025). "Our results demonstrate that CYP24A1 activity, estimated by VMDR, is directly linked to urine calcium excretion, kidney stone composition, and BMD at the femoral neck." (PMID 38765596, 2024). "Despite these limitations, our analyses significantly extend current knowledge on the role of the vitamin D-inactivating enzyme CYP24A1 in nephrolithiasis." (PMID 38765596, 2024). "In a cohort of patients with kidney stones, high normal serum Ca and low normal PTH concentrations, nine known sequence variants of the CYP24A1 gene were detected." (PMID 26332888, 2015). "The observation that 28 of 547 (5 %) of vitamin D-replete kidney stone formers in our cohort had a VMDR >25 indicates that other factors may play an important role in the regulation of CYP24A1 activity." (PMID 38765596, 2024).
prostate carcinoma (30 papers, 2008 to 2025). A carcinoma that arises from epithelial cells of the prostate gland. "A previous meta-analysis also reported CYP24A1 rs2296241 polymorphism was associated with prostate cancer risk." (PMID 37670334, 2023). "Comparatively, in primary cancers, a high CYP24A1 expression has been associated with poor cancer cell differentiation in prostate cancer and a poor clinical outcome in lung and colon cancers." (PMID 36362766, 2022). "Hypermethylation of the CYP24A1 promoter region, with associated epigenetic silencing of CYP24A1 expression, has been identified in prostate cancer cell line PC3 and tumor-derived endothelial cells (TDEC)." (PMID 33291213, 2020). "In the DU145 prostate cancer cell line, CYP24A1 is overexpressed causing resistance to 1,25D(OH)2D3-mediated growth inhibition unless CYP24A1 activity is blocked by inhibitors." (PMID 28591703, 2017). "The minor allele of the CYP24A1 gene SNP rs927650 has been reported to be associated with a decreased risk of disease recurrence/regression in prostate cancer patients." (PMID 22576141, 2012). "The polymorphism rs927650 that is analyzed in our present study, as well as another polymorphism (rs2762939) in the CYP24A1 gene were significantly associated with prostate cancer prognosis." (PMID 22576141, 2012). "Besides, one of the main vitamin D-related genes, CYP24A1 was found to be negatively associated with the prognosis of prostate cancer." (PMID 34035992, 2021). "Moreover, associations of SNPs in the CYP24A1 gene with prostate cancer prognosis have been reported." (PMID 22576141, 2012). "Potentially, overexpression of CYP24A1 could induce vitamin D resistance and promote risk for prostate cancer." (PMID 21991434, 2011). "ADORA2A and CYP24A1 demonstrated therapeutic drug synergies in advanced prostate cancer when targeted in combination with existing treatments, PARP inhibitors and calcitriol, respectively." (PMID 38983753, 2024). "It was revealed that knocked-down of CYP24A1 gene by siRNA rendered prostate cancer cells to be more sensitive to the growth-suppressive effect of vitamin D3." (PMID 36527000, 2022). "Inhibition of CYP24A1 had enhanced the anti-proliferation effect and promoted the activation of caspase-independent apoptosis pathway in prostate cancer cells when exposed to calcitriol." (PMID 36527000, 2022). "Intriguingly, CYP24A1 expression has been found to be significantly higher in malignant tumours of prostate, lung and colorectal cancers compared to benign tumours." (PMID 36362766, 2022). "It is also known that the serine/threonine protein kinase casein kinase 2 (CK2) signaling pathway stimulates overexpression of CYP24A1 in prostate cancers." (PMID 34208589, 2021). "The gene polymorphisms of CYP24A1 and CYP17A1 have been closely correlated with the risk of liver, lung, stomach, and prostate cancers in a Chinese population." (PMID 34522968, 2021). "For example, histone modification and DNA methylation cooperatively regulate the expression of UGT1A1 in the kidney and inhibit the expression of cytochrome P450 family 24 subfamily A member 1 (CYP24A1) in prostate cancer cells." (PMID 34034810, 2021). "The trial study of CYP24A1 inhibitor in prostate cancer treatment has been examined to improve VD3 efficacy." (PMID 32831047, 2020). "CYP24A1 has been shown to be overexpressed in cancer cells while activity of CYP27B1 is reduced in human prostate cancer cells." (PMID 31749811, 2019). "Variants in VDR, CYP24A1, and CYP27B1 were associated with progression to prostate cancer-specific mortality in a case-only study (n = 1,294)." (PMID 25488826, 2015). "In prostate cancer cells, the methylation status of CYP24A1 promoter inversely correlated with gene expression." (PMID 24808866, 2014). "Polymorphisms in the vitamin D metabolism-related genes CYP24A1 and CYP27B1 were reported to be associated with colon as well as prostate cancer risk, respectively." (PMID 22576141, 2012).
prostate carcinoma (continued). "We also observed correlations between ESS2 and CYP24A1 expression in patients with prostate cancer." (PMID 37524814, 2023). "The effects of 1,25-VD on the mRNA expression levels of HIST1H1C, HFE, SGCZ, TUSC3, and CYP24A1 (cytochrome P450 family 24 subfamily A member 1), a well-known 1,25-VD target gene, were examined using quantitative real-time polymerase chain reaction (qRT-PCR) in PC-3 human prostate cancer cells." (PMID 29088772, 2017). "As previously reported in prostate cancer cells, VD3 treatment induces CYP24A1 as well, an enzyme that catalyzes VD3 to its inactive form." (PMID 32831047, 2020). "In the human prostate cancer cell line PC3, methylation of the CYP24A1 promoter reduced reporter gene expression in a methylation-dependent manner." (PMID 24808866, 2014). "Among these targets, five of them (A2AR/ADORA2A, CSK, CYP24A1, BRDT, and BRAF) have been suggested in recent scientific papers to be related to prostate cancer and all can interact with ligands with known therapeutic advantages against advanced prostate cancer." (PMID 38983753, 2024). "Furthermore, CYP24A1 was identified as potential oncogene in breast cancer and elevated expression of VDR in tissues of breast and prostate cancer correlates with better prognosis of survival." (PMID 31749811, 2019). "In turn, the greater effect on MMP-9 gene expression and the expression of CYP24A1 and genes involved in cell proliferation may be due to its more profound VDR transactivation activity in prostate cancer cells." (PMID 22084796, 2011). "However, opposite data have been also published for prostate cancer and a negative correlation between expression of CYP24A1 and tumor progression has been observed in melanoma." (PMID 34208589, 2021). "Prostate cancer cells (LNCaP and 22Rv1) showed low to no expression of CYP27B1 (encoding a vitamin D 25-hydroxylase) and were unable to metabolize 25D to the active hormone 1,25D, as shown by the lack of CYP24A1 (encoding vitamin D 24-hydroxylase) induction by 25D." (PMID 36875158, 2023). "Thus, a CYP24A1 resistant VDR agonist may be beneficial for treatment of TMPRSS2:ERG positive prostate cancer; one negative consequence of TMPRSS2:ERG expression is inactivation of VDR signaling." (PMID 28591703, 2017).
Hypercalciuria (28 papers, 2015 to 2025). "The successful use of rifampicin to provide an alternative pathway of vitamin D catabolism has been reported in patients with an impaired function of their CYP24A1, which is linked to idiopathic hypercalcemia, significantly improving serum calcium and hypercalciuria." (PMID 39337491, 2024). "Indeed, hypercalciuria and the risk of renal stones continue in most subjects with CYP24A1 mutations throughout adult life." (PMID 35956396, 2022). "Additionally, it was recently uncovered that patients with either hereditary hypophosphatemic rickets with hypercalciuria or CYP24A1 deficiency show a high incidence of renal cysts." (PMID 36523654, 2022). "Furthermore, the treatment of CYP24A1-deficient patients with ketoconazole and fluconazole alleviated hypervitaminosis D, leading to the normalization of their serum calcium and hypercalciuria." (PMID 39337491, 2024). "Our study reveals that CYP24A1 activity, estimated by VMDR, is associated with clinical traits previously linked to idiopathic hypercalciuria." (PMID 38765596, 2024). "Further evidence supporting biologic actions of high 1,25-vitamin D included changes in renal Cyp24a1, Trpv5, and Calbindin D28k expression; circulating intact and C-terminal FGF23 levels; and hypercalciuria." (PMID 36862513, 2023). "Different monogenic polymorphisms have been proposed as playing a causal role for calcium nephrolithiasis, including the VDR gene, CYP24A1, and SLC34A1; however, the complete pathogenetic pathway of hypercalciuria is yet to be determined." (PMID 34959915, 2021).
nephrocalcinosis (25 papers, 2018 to 2025). Nephrocalcinosis is a disorder that occurs when too much calcium is deposited in the kidneys. "CYP24A1 disease causing variants lead to nephrocalcinosis and calcium stone formation, and conventional treatments for calcium stones are recommended." (PMID 40917505, 2025). "Following further analysis, two distinct phenotypes resulting from CYP24A1 mutations have been recognised, both of which frequently include nephrocalcinosis." (PMID 31935940, 2020). "In addition, several publications have reported adolescent and adult patients with identical bi-allelic mutations in CYP24A1, who mainly presented with recurrent kidney stone disease or nephrocalcinosis, typically during childhood or adolescence." (PMID 34858904, 2021). "In biallelic disease, adult presentations may occur also, often triggered by pregnancy or exposure to vitamin D. Patients with a single (monoallelic) CYP24A1 variants tend to present with kidney stone disease and less frequently with nephrocalcinosis and symptomatic hyercalcaemia." (PMID 40917505, 2025). "Although disease causing variants in CYP24A1 are rare, there is growing evidence that disease phenotypes, especially in monoallelic patients, may include late adult presentations of kidney stone disease and nephrocalcinosis." (PMID 40917505, 2025). "Similar to patients with CYP24A1 mutations, an azole antifungal agent (ketoconazole or fluconazole) may be used to inhibit 1α-hydroxylase, thereby reducing the high calcium levels predisposing to nephrocalcinosis through reduction in levels of 1,25-dihydroxyvitamin D3." (PMID 31935940, 2020). "Mutations of CYP24A1 and SLC34A1 are known to cause infantile hypercalcemia (IH) types 1 and 2, respectively, which are autosomal recessive disorders of calcium and phosphate metabolism associated with nephrocalcinosis and KSD." (PMID 40372791, 2025). "In patients with nephrocalcinosis (n=55; 44 children and 11 adults), we identified 18 (33%) patients with biallelic class IV or V variations, mostly in CYP24A1 (n=25/28) and also in SLC34A3 (n=3/28); 4 adults with biallelic CYP24A1 mutations presented chronic kidney disease (CKD-EPI<60mL/min)." (PMID 34721296, 2021). "Mutations in a heterozygous state were found in patients with renal stones (n=6), nephrocalcinosis (n=4) and no renal complications (n=5), mostly in CYP24A1 (n=9) and SLC34A3 (n=5)." (PMID 34721296, 2021).
melanoma (24 papers, 2011 to 2025). A malignant, usually aggressive tumor composed of atypical, neoplastic melanocytes. "CYP24A1 protein levels are inversely linked with poor clinical outcomes in patients with melanoma." (PMID 38672780, 2024). "In addition, the presence of specific polymorphisms of VDR or a decreased expression of VDR, CYP27B1, CYP24A1 and defects in vitamin D signaling are linked to more advanced stages of melanoma or poorer prognosis." (PMID 30200275, 2018). "In our present hospital-based case–control study, we tested eight vitamin D metabolism-related polymorphisms focusing on the VDBP gene (rs1155563 and rs7041) and the genes coding for CYP27B1 and CYP24A1 (rs4646536 and rs927650) for their association with melanoma risk and melanoma prognosis." (PMID 22576141, 2012). "The current study shows that both CYP24A1-derived metabolites, 20,24(OH)2D3 and 1,24,25(OH)3D3, inhibit the proliferation of human melanoma A375 cells maximally by about 25%, while for SK-MEL-28 cells this effect was markedly weaker." (PMID 39456696, 2024). "Consistent with our previous results, we observed a profound increase in the mRNA level for CYP24A1 in A375 melanoma cells treated with 1,25(OH)2D3 (p < 0.001)." (PMID 38473753, 2024). "For example, products of CYP24A1 hydroxylation (20,24(OH)2D3, 20,25(OH)2D3, and 20,26(OH)2D3) were more potent at inhibiting melanoma growth than their precursor 20(OH)D3." (PMID 38927967, 2024). "A slight (greater than 2-fold) increase in the mRNA level for CYP24A1 was also observed in A375 melanoma cells treated with CPL304110 (p < 0.05) and the effect was strongly enhanced by 1,25(OH)2D3." (PMID 38473753, 2024). "Melanomas stratified according to their Breslow thickness, Clark level, pT, and overall stage also showed the lowest CYP24A1 level in the most advanced melanomas (Clark levels IV-V, Breslow thickness > 2 mm, pT3-4, stage 3–4)." (PMID 38927967, 2024). "A clinical pathology study with melanoma patients found that the occurrence of ulceration, necrosis, nodular type, and amelanotic phenotypes was related to lower CYP24A1 levels." (PMID 38672780, 2024). "While CYP24A1 levels were high in nevi and early-stage melanomas in comparison to normal epidermis, its level decreased during melanoma progression similarly to CYP27B1 and VDR." (PMID 34692525, 2021). "In fact, the mRNA level of CYP24A1 was the highest in melanoma cells treated with cediranib following vitamin D pretreatment (p < 0.01 vs. monotreatment)." (PMID 35004285, 2021). "Lastly, consistent with our previous results and literature data, we observed a marked increase in mRNA level for CYP24A1 (p < 0.01) in melanoma cells treated with 1,25(OH)2D3." (PMID 35004285, 2021). "The high levels of CYP24A1 also positively correlated with a poor outcome of cancers including ovarian, prostate, breast, thyroid, colorectal cancers and melanomas." (PMID 32850381, 2020). "In the case of CYP24A1, together with an increase of VDRn in the melanoma to the level of about 40, the CYP24A1 value also increased." (PMID 31235702, 2019). "CYP24A1, a mitochondrial monooxygenase belonging to the cytochrome P450 – superfamily, was found to be expressed in melanoma cells (90.32%), normal uveal melanocytes (67.74%) and other normal cells (54.84%) of the choroid coat." (PMID 31235702, 2019). "In our study we confirmed the presence of CYP27B1 and CYP24A1 in the melanoma cells and their connection with the VDR level." (PMID 31235702, 2019). "Paradoxically, elevated levels of CYP24A1 have been reported in melanocytic nevi and early stage melanomas, highlighting the complex role of CYP24A1 in skin tumorigenesis." (PMID 28211524, 2017). "CYP24A1 is an enzyme that can metabolize vitamin D3 to generate biologically active hydroxyderivatives with efficient anti-tumorigenic activities on melanoma cells." (PMID 28211524, 2017).